PSD (pleckstrin and Sec7 domain containing)
Description:
Guanine nucleotide exchange factor for ARF6. Induces cytoskeletal remodeling (By similarity).
Synonyms: EFA6; EFA6A; KIAA2011; PSD1; TYL
Tractability: Small molecule: a high-quality ligand is known. Antibody: UniProt places it where antibodies can reach, with high confidence; its Gene Ontology location is reachable by antibodies, with medium confidence. PROTAC: its protein half-life has been measured; a small molecule that binds it is known.
Gene: Protein-coding gene on chromosome 10 (102,402,614 to 102,421,539, reverse strand). Ensembl gene ENSG00000059915.
Subcellular location: Cell membrane; Cell projection, ruffle membrane; Cleavage furrow
Gene Ontology:
Molecular function: guanyl-nucleotide exchange factor activity; protein binding; phospholipid binding
Biological process: signal transduction; neuron projection development; regulation of ARF protein signal transduction
Cellular component: cleavage furrow; plasma membrane; ruffle membrane; dendritic spine; postsynaptic density; postsynaptic density, intracellular component
Genetic constraint (gnomAD): Loss-of-function variants: 34 observed, 89.9 expected, observed/expected ratio (o/e) 0.38, 90% interval 0.29 to 0.5. The upper end of that interval is the gene's LOEUF score, 0.5, which puts it in group 2 of 6, group 1 being the genes least tolerant of losing a copy. Missense variants: 1,099 observed, 1,370.2 expected, observed/expected ratio (o/e) 0.8, 90% interval 0.76 to 0.84. Synonymous variants: 532 observed, 572.89 expected, observed/expected ratio (o/e) 0.93, 90% interval 0.86 to 1.
Homologues: Orthologues: chimpanzee PSD (99% identical), macaque PSD (99% identical), dog PSD (95% identical), pig PSD (93% identical), mouse Psd (92% identical), guinea pig PSD (91% identical), rat Psd (90% identical), rabbit PSD (73% identical), tropical clawed frog PSD (36% identical), zebrafish psda (31% identical), Drosophila melanogaster Efa6 (29% identical), Caenorhabditis elegans efa-6 (19% identical). Paralogues in human: PSD2 (34% identical), PSD3 (34% identical), PSD4 (29% identical), IQSEC1 (15% identical), IQSEC2 (15% identical), IQSEC3 (15% identical), MON2 (14% identical), ARFGEF1 (12% identical), GBF1 (12% identical), ARFGEF2 (12% identical), CYTH1 (10% identical), CYTH3 (10% identical), and 3 more.
Diseases named in the same sentence as PSD in open-access papers:
PSD is named in the same sentence as 34 diseases in open-access papers, as found by Europe PMC text mining. Sharing a sentence is not in itself a finding about the gene and the disease. The quoted sentences say what the papers report.
schizophrenia (4 papers, 2017 to 2021). A major psychotic disorder characterized by abnormalities in the perception or expression of reality. "Furthermore, pathway analysis of common variants from GWAS data have implicated PSD genes as having a prominent role in schizophrenia and BD45,46." (PMID 29531218, 2018). "We also found these genes were significantly enriched in FMRP and PSD gene sets, which have been previously reported implicated in schizophrenia, demonstrating the effectiveness of our multi-SNP integrative MAGMA strategy in identify schizophrenia risk loci and genes." (PMID 34021155, 2021).
Stroke (2 papers, 2021 to 2024). Sudden impairment of blood flow to a part of the brain due to occlusion or rupture of an artery to the brain. "DV treatment was delayed until PSD 7 in order to determine whether it could have a broad therapeutic window for experimental stroke as well as to distinguish potential DV effects on neurorepair mechanisms from more acute (e.g., PSD1 to PSD 3) neuroprotective effects." (PMID 32253702, 2021).
autism (1 paper, 2020). Persistent deficits in social interaction and communication and interaction as well as a markedly restricted repertoire of activity and interest as well as repetitive patterns of behavior. "As such, changes in the expression of PSD genes have been associated with disorders such as autism and schizophrenia." (PMID 32994467, 2020).
autism spectrum disorder (1 paper, 2018). A spectrum of developmental disorders that includes autism, and Asperger syndrome. "The PSD genes are extremely sequence conserved, and comprise scaffolding proteins, such as SHANK3 and NRXN1 genes, which are recurrently described with mutations in autism spectrum disorder and schizophrenia." (PMID 29531218, 2018).
colorectal cancer (1 paper, 2012). A primary or metastatic malignant neoplasm that affects the colon or rectum. "We previously reported that the Pleckstrin and Sec7 domain-containing (PSD) gene is preferentially methylated in patients with ulcerative colitis (UC) who developed colorectal cancer (CRC), and is implicated in UC-associated carcinogenesis through its inhibition of apoptosis." (PMID 22179719, 2012).
diabetes (1 paper, 2009). "CD1D is a transmembrane protein involved in the presentation of lipid antigens to T cells and known to contribute to the generation of diabetes, and PSD belongs to a family of intracellular signal transduction proteins known to increase insulin sensitivity." (PMID 19961616, 2009).
ischemic stroke (1 paper, 2021). A stroke disorder caused by obstruction of blood flow to the brain, due to thrombotic (local blood clot formation) or embolic (due to a blood clot or other material traveling from another site) event. "The densities of SYP+ presynapse, PSD+ postsynapse and SYP+/PSD95+ synapse were increased in microglial and astroglial cKO mice after ischemic stroke, as compared with the control." (PMID 34836962, 2021).
retinal degeneration (1 paper, 2020). Degeneration of the retina. "Homozygous mutations in PSD genes cause a range of conditions, including skeletal dysplasia, early-onset retinal degeneration, hearing loss, microcephaly, and intellectual disability." (PMID 33064773, 2020).
Type I Diabetes (1 paper, 2009). "The TSP prediction rule to diagnose Type I Diabetes is based on the relative expression of the genes CD1D and PSD." (PMID 19961616, 2009).
PSD also shares sentences with these, for which no sentence is quoted: tumor (4 papers); cancer (3); infection (3); candidiasis (2); glioma (2); renal carcinoma (2); bipolar disorder (1); breast carcinoma (1); Cognitive impairment (1); colitis (1); cyst (1); depressive syndrome (1); epidermoid carcinoma (1); fungal infection (1); Hallucinations (1); infectious disease (1); insomnia (1); melanoma (1); metastatic melanoma (1); neurodevelopmental disorder (1); neurologic disorders (1); ovarian carcinoma (1); retinal ciliopathies (1); skin melanoma (1); ulcerative colitis (1).